CD4 (CD4 molecule)
Diseases named in the same sentence as CD4 in open-access papers (continued):
Sharing a sentence is not in itself a finding about the gene and the disease.
breast cancer (continued). "Relevant to clinical translation, LAIT also upregulated genes in CD8+ and CD4+ T cells that positively correlated with extended survival of breast cancer patients." (PMID 35808806, 2022). "Previously, we have demonstrated that thymic stromal lymphopoietin (TSLP), an epithelium-derived cytokine and a master regulator of allergic inflammation in barrier organs, blocks breast cancer development through the activation of CD4+ T cells." (PMID 35657353, 2022). "We also observed that the frequency of T cells in CA was much higher than that in ADJ among total breast cancer patients, while the frequencies of CD4+T, CD8+T, and DNT cells in CA were comparable with those in ADJ." (PMID 35894707, 2022). "It was identified as an abundant protein in breast tumors and correlates with aggressiveness and metastasis of breast cancer because it enhances the pro-tumor Th2 response and triggers the expansion of CD4+ CD25+ Foxp3+ Tregs cells." (PMID 35335881, 2022). "Our findings reveal a critical role for CD4+ Th2 cells in immunity against breast cancer, which is mediated by terminal differentiation as a distinct effector mechanism for cancer immunoprevention and therapy." (PMID 35657353, 2022). "The results indicated that IGF2BP3 expression was positively correlated with infiltration of CD8+, CD4+ T cells, and B cells in each of the breast cancer subtypes, which was similar to the effect of PD-L1 (CD274)." (PMID 35197058, 2022). "When these enzymes accumulate, they can weaken T cell immunity in breast cancer patients by suppressing CD4+ and CD8+ T cells, which worsens relapse-free and overall survival." (PMID 35954312, 2022). "An elevated CD4/CD8 was found to be associated with tumor progression and poor survival in breast cancer patients." (PMID 35626709, 2022). "The dominance of infiltrated CD4+ T lymphocytes and lower levels of CD8+ T cells in breast cancer tissue have been associated with poor survival." (PMID 35051220, 2022). "To determine the mechanism by which TSLP-stimulated CD4+ T cells suppressed breast carcinogenesis, we examined spontaneous breast cancer development in K14-Tslptg, MMTV-PyMTtg (Tslp-PyMttg) mice compared with PyMttg controls on the BALB/c background." (PMID 35657353, 2022). "An immunotolerant pathway activity profile was identified in CD4+ T cells from tumor infiltrate and blood of a subset of primary breast cancer patients, which was most similar to the pathway activity profile in immunosuppressive Treg cells." (PMID 35158758, 2022). "In contrast to early breast cancer suppression, the antitumor immunity mediated by TSLP-stimulated CD4+ T cells in advanced breast cancer is mediated by the induction of a senescent-like phenotype in cancer cells." (PMID 36467403, 2022). "Our findings demonstrate that TSLP-stimulated CD4+ T cell immunity blocks breast cancer promotion by engulfing primary breast tumors and transforming them into low-grade, fibrocystic structures, with no metastatic potential." (PMID 35657353, 2022). "There were strong correlations between TRIM8 copy numbers and immune cell infiltration, such as macrophage in breast cancer, CD4+ T Cell, and Macrophage in luminal-type breast cancer." (PMID 35368651, 2022). "To determine the mechanism of breast cancer suppression by CD4+ T cells, we assessed apoptosis in early breast tumors of Tslp-PyMttg versus PyMttg mice using terminal deoxynucleotidyl transferase dUTP nick-end labeling (TUNEL) and cleaved caspase 3 assays." (PMID 35657353, 2022). "To further define the impact of CD4+ T cell immunity on breast cancer cells, we compared the transcriptome of advanced breast tumors from Tslp-PyMttg Rag1KO + CD4+ T cell (test) and PyMttg Rag1KO + CD4+ T cell (control) groups." (PMID 35657353, 2022). "Related to the main components of tumor-infiltrating immune cells isolated from breast cancer CD4+ and CD8+ T cells are the most abundant immune cells, but B cells also make up a significant proportion of immune cells." (PMID 35454849, 2022).
breast cancer (continued). "We have previously demonstrated that the induction of Thymic Stromal Lymphopoietin (TSLP) leads to a robust antitumor CD4+ T helper 2 (Th2) cell immunity that suppresses skin and breast cancer development." (PMID 35565302, 2022). "The progression of breast cancer is characterized by increased immune cell infiltration in tumor parenchyma and stroma, including CD4+ and CD8+ granzyme B+ cytotoxic T cells, B cells, macrophages and dendritic cells." (PMID 35953532, 2022). "There should be a positive relationship between CD52 expression and activated memory CD4+ T cells in breast cancer." (PMID 36457341, 2022). "Breast cancer suppression in the test group was associated with large CD4+ T and few CD103+ CD4+ TRM cell infiltrates surrounding the low-grade tumors." (PMID 35657353, 2022). "Inflammatory CD4+ T cells drive breast cancer cells into senescence by releasing interferon-gamma and tumor necrosis factor-alpha, which directly bind to their receptors on cancer cells." (PMID 36467403, 2022). "BMI change since age 18 was positively associated with novel CD4+ and CD163+ cell scores in breast cancer, supporting further study of the effect of modifiable factors like weight gain on the immune microenvironment." (PMID 36376974, 2022). "CD4+ T cell infiltration was similar to that of CD8+ T cells (range of 5.9 × 103 to 4.7 × 106, median of 3.1 × 105 CD4+ T cells/gram of tumor), with lower infiltration of breast-carcinoma metastases." (PMID 35584630, 2022). "In view of the importance of Th1/Th2 balance in breast cancer progression, our findings suggest that CD4+ TNFR2+ PD-1+ were either exhausted Th1 cells or activated Th2 cells, whose levels were reduced by chemotherapy." (PMID 34201054, 2021). "The S100A8/A9-mediated ROS suppression was reported to improve the CD4+ T cell accumulation in TME of breast cancer, which has been known to be regulated in STAT3-dependent mechanism in MDSCs." (PMID 33957948, 2021). "Later their group found that tumor-infiltrating CD4+CD25+FOXP3+ T cells were a major source of RANKL production in breast cancer and stimulated breast cancer metastasis through RANKL–RANK signaling." (PMID 33795653, 2021). "Other studies have also evaluated the relationship between CD8+ cytotoxic T cells, CD4+ T cells, and immunotherapy response in breast cancer." (PMID 34944679, 2021). "A distinct population of Nrp1+ Treg cells, characterized by CD4+CD25highFoxp3+, was present in mammary tumors of MMTV-PyVT mice treated with adiponectin-expressing EGFP+ cells." (PMID 33727658, 2021). "To further determine the in vivo anti-tumor efficiency of ex vivo activated CD4+T cells, we have utilized a Py230 breast cancer cell based orthotopic syngeneic murine model." (PMID 33918403, 2021). "The increased HPSE expression correlated with poor prognosis and increased immune infiltration levels of B cells, CD8+ and CD4+ T cells, macrophages, neutrophils and dendritic cells in bladder and breast cancer." (PMID 34461608, 2021). "Here, we found that YTHDF1 expression was distinctly related to T cells CD4 memory activated, macrophages M1, NK cells activated, and monocytes in breast cancer tissues." (PMID 34434939, 2021). "Based on the different subtypes of BRCA, we observed that ceruloplasmin expression was significantly associated with the infiltration abundances of CD4+ T cells, CD8+ T cells, neutrophils, macrophages, and dendritic cells in luminal A breast cancer." (PMID 34413268, 2021). "For example, as reported in breast cancer, blocking the recruitment of naïve CD4+ T cells into tumor significantly reduces intratumoral regulatory T cells and inhibits tumor progression." (PMID 33391397, 2021). "TFH constitute 40% of the PD-1+ CD4+ TIL in breast cancer, suggesting a prominent role in the anti-breast cancer immune response." (PMID 33467084, 2021).
breast cancer (continued). "The most pronounced influence of MCF-7 breast cancer cells on lymphocytes was found when analyzing CD4+CTLA-4+/PD-1+ and CD8+CTLA-4+/PD-1+ frequencies in total lymphocytes." (PMID 34440813, 2021). "We also found that the CD4+ T cells were identified by the XAI as the third most influential immune cell type on the breast cancer prognosis." (PMID 34298668, 2021). "To explore the possible contribution of the KLRG1+CD57+ CD4+ T cell subset in the clinical prognosis of breast cancer, we collected publicly available TCGA datasets of patients with breast carcinoma to link gene expression data with overall survival (OS)." (PMID 34386013, 2021). "This induction of a strong OV-induced CD4 T cell response has been demonstrated before in a breast cancer mouse model treated with a targeted replicating recombinant vesicular stomatitis virus (rrVSV)." (PMID 33665363, 2021). "The Tim-3 level in circulating Tfh (CD4+CXCL13+follicular helper T) cells in patients with breast cancer was significantly elevated, which was a Tfh exhaustion marker." (PMID 34504800, 2021). "Previous studies have reported the crucial role of CXCL13 in follicular helper T cells and B cells recruitment, and intratumora CXCL13-producing CD4+ follicular helper T cells were relevant for prognosis in breast cancer." (PMID 34122408, 2021). "In breast cancer, it was reported that the presence of disseminated tumor cells after NACT was significantly associated with higher levels of CD4+ T cells located in the tumor center pre-NACT." (PMID 34697289, 2021). "EGCG also inhibited the proliferation of breast cancer cells by significantly reducing the accumulation of MDSCs and increasing tumor infiltration of CD4+ and CD8+ T cells in 4T1 breast tumor-bearing mice." (PMID 33572626, 2021). "Through TIMER analysis, we found a positive correlation between RUNX1 gene copy number and the infiltration of B cells, CD8+T cells, CD4+T cells, macrophages, neutrophils, and dendritic cells in breast cancer." (PMID 34485309, 2021). "The role of Sos1 as a regulator of cell migration has been described in macrophages, glioblastoma cells breast cancer cells, peripheral CD4(+) T cells, etc." (PMID 33889087, 2021). "IFNγ and FOXP3 expressions were detected in cells cocultured with CD4 T cells and breast cancer cells." (PMID 34659411, 2021). "The results showed that RUNX1 mutations significantly increased the levels of CD8+T cells, CD4+T cells, and macrophage infiltration in breast cancer." (PMID 34485309, 2021). "Alisertib has been shown to alter the immunosuppressive state by eliminating MDSCs via apoptosis and to enhance antitumor immunity by increasing CD8+ and CD4+ T cell abundance, leading to the regression of mouse mammary tumors." (PMID 34638242, 2021). "Solomayer and colleagues reported that chemotherapy exerts a particularly suppressive effect on naïve CD4 T cells and, to a lesser extent, on memory CD4 T cells in patients with breast cancer." (PMID 34113569, 2021). "Next, we analyzed immune cells (B cell, CD8+ T cell, CD4+ T cell, macrophages, neutrophils, and dendritic cells) on the prognosis in breast cancer, the expression of these immune cells was divided into high and low levels by using the median expression." (PMID 34020650, 2021). "The role of CD4+ TILs in breast cancer is complex and the numbers and cell subsets of CD4+ T cells dynamically changed with breast cancer progression." (PMID 34858823, 2021). "Inactivation of STAT3 contributed to breast cancer immunogenic phenotype, which involved the participation of CD4+ T cells and NKs, and decreased Tregs in the TME." (PMID 33957948, 2021). "The results showed that the expression of VWCE was significantly correlated with tumor purity and infiltration level of CD4+ T cell, macrophages, and dendritic cell in breast cancer." (PMID 34020650, 2021). "In breast cancer, Th2-like CD4+ T cells protected tumors from chemotherapy and induced metastasis by inducing M2-like TAM polarization." (PMID 34283809, 2021).
breast cancer (continued). "Specifically, it has been reported that the lymph nodes had an enhanced infiltration proportion of memory CD4 T cells in breast cancer." (PMID 33714943, 2021). "We also found that RUNX1 mutations in breast cancer significantly increased the infiltration of CD8+T cells, CD4+T cells, and macrophages in breast cancer." (PMID 34485309, 2021). "The expression of Tim-3 in CD4+ T cells was also upregulated in breast cancer, and correlated with metastatic lymph node load, suggesting its importance in suppressing the immune microenvironment." (PMID 34504800, 2021). "Bregs are the immunosuppressive lymphocytes, which have been shown to promote breast cancer metastasis by inducing the conversion of resting CD4+ T cells into Tregs." (PMID 33682324, 2021). "In contrast to previous studies using the CDK4/6 inhibitor Abemaciclib in a breast cancer model as well as in CT-26 tumor-bearing mice, we did not observe a selective decrease in the frequency of Tregs within CD4+ T cells." (PMID 34248938, 2021). "A recent study showed that the specific targeting of TGFβ signaling in CD4 T cells, via a TGFBR2 coupled to a CD4 antibody induces an anti-tumor response mediated by IL-4 in a mouse breast cancer model." (PMID 33498483, 2021). "TCR repertoire analysis on CD4+ T cells from tumor, blood, and lymph nodes of five breast cancer patients revealed that tumor-infiltrating Tregs are most similar to naïve CD4+ T cells from tumor and blood, suggesting intratumoral conversion." (PMID 34632244, 2021). "Treatment with endocrine therapy using the aromatase inhibitor letrozole increases CD4+ T cell infiltration into ER+ breast cancer tumours in immune competent mice." (PMID 34602068, 2021). "The characteristics of CD4+CXCL13+ T cells in LR-CHL are very similar to a CXCL13-producing TFH population that lacks CXCR5 expression identified in breast cancer." (PMID 34615710, 2021). "Th17 cells, another subtype of CD4+ T helper cells, promote endothelial cell proliferation and tumor angiogenesis by expressing IL-17, a poor prognostic factor in breast cancer." (PMID 34294146, 2021). "In systemically untreated breast cancer patients, CD4+ T cells were found to be the principal component of the tumor infiltrating lymphocytes (TIL) and along with TH1, TH2 and TH17 subtypes, were also enriched for Tfh populations." (PMID 34012451, 2021). "Oestrogen deprivation of breast cancer cells increases migration of CD4+ T cells and decreases migration of CD11c+ and CD14+ PBMC towards cancer cells." (PMID 34602068, 2021). "CD4, CD25 T cells are associated with a poor prognosis in breast cancer and correlate with the expression of FOXP3, a tumor-promoting CD4 T cell, also termed regulatory T cells." (PMID 34638488, 2021). "The expression of CD8 (the intratumoral P=0.017, the peritumoral P<0.001) in primary sites and CD3 (P=0.003) and CD4 (P=0.004) in the peritumoral primary sites were higher than that in normal breast cancer." (PMID 34858823, 2021). "Breast cancer patients harbor in PB IFNγ-producing CD4+Teff but also suppressive CD4+Treg reactive to MAMI33,35,36." (PMID 33602930, 2021). "Naïve CD4 T cells were developed to form Treg cells in the tumor microenvironment and predicted poor prognosis in breast cancer." (PMID 34277706, 2021). "A phase II trial of rhIL-7 in lymphopenic metastatic breast cancer patients has demonstrated a significantly increased CD4+ and CD8+ T-cell count." (PMID 34960140, 2021). "Using the TIMER database, we analyzed the correlation between the expression levels of RUNX protein family members and the infiltration of B cells, CD8+T cells, CD4+T cells, macrophages, neutrophils, and dendritic cells in different breast cancer subtypes." (PMID 34485309, 2021). "HSP‐related genes have been shown to be highly expressed in regulatory T cells (Treg) and CD4+ conventional T (Tconv) cells in breast carcinoma compared to normal breast parenchyma." (PMID 33463049, 2021).
breast cancer (continued). "CD4+ T effector cells that express high levels of IL-13 accelerated development of mammary carcinomas and their metastasis to the lung by enhancing pro-tumorigenic potential of tumor-associated macrophages." (PMID 33686176, 2021). "The results revealed that highly enriched cDC, NKT, CD8+ T-cells, CD8+ Tcm, CD4+ Tem cells led to better overall survival in breast cancer, while the immunescore and other immune cell types enrichment scores didn’t show prognosis significance." (PMID 32070368, 2020). "Regulatory CD4+ T cell (Treg) is one of the suppressive immune cells, but data on its clinical relevance in large human breast cancer cohort is limited." (PMID 33086518, 2020). "During the development of breast cancer, the human immune system is activated, and both CD4+ and CD8+ TE cells are mobilized to fight tumor cells." (PMID 33061819, 2020). "The number of CD4+CD25+Tregs in patients with breast cancer was found to decrease after chemotherapy or radiotherapy." (PMID 33029539, 2020). "This study used longitudinal live cell imaging to quantify the effect of immune cell presence on trastuzumab-treated HER2 + breast cancer through in vitro co-culturing of CD4 + T-cells and HER2 + cancer cell lines." (PMID 33292267, 2020). "This is in line with a study in breast cancer patients that reported decreased numbers of CD4+ T cells and B cells even 9 months after completion of chemotherapy." (PMID 32399587, 2020). "High NRF2 expression ER-positive/HER2-negative breast cancer was associated with increased tumor-infiltrating lymphocytes (CD8+ T cell, CD4+ T cell, and DC) and low fraction of Th1 cells." (PMID 33371179, 2020). "Using a Western diet-induced outbred Swiss mouse model and an FVB strain Her2-mutant spontaneous breast cancer model, it has been shown that oral administration of Lactobacillus reuteri inhibits mammary tumorigenesis by CD4+CD25+ lymphocyte stimulation." (PMID 32354130, 2020). "Immunity in breast cancer remains largely unstudied with only a few preliminary evaluations on the prognostic value of CD4+/CD8+ T lymphocytes." (PMID 32728493, 2020). "Further, we observed that the administration of Y‐27632 in breast cancer mice increased CD4+ CD8 + T‐cell infiltration in tumor, indicating that T‐cell infiltration contributes to tumor regression." (PMID 32941674, 2020). "Inhibiting the recruitment of T-cell CD4 naive into tumors reverses immunosuppression in breast cancer." (PMID 32793475, 2020). "Prostaglandin E2 produced by MCF7 breast cancer cells stimulated upregulation of SERCA3 expression in CD4+ T cells, leading to ER stress and CD4+ T cell apoptosis." (PMID 32825277, 2020). "Although clinical studies have shown that successful trastuzumab therapy is associated with immune cell infiltration, there exists a lack of longitudinal studies that examine trastuzumab-induced CD4 + immune interaction with HER2 + breast cancer." (PMID 33292267, 2020). "A detailed analysis of bronchoalveolar lavage showed a dramatical increase of lymphocytes, mainly including the CD4+ T lymphocytes, in breast cancer patients with RP after irradiation." (PMID 32207253, 2020). "In breast cancer 103 and bladder cancer 104, tumor-infiltrating naive CD4+ T cells were correlated with poor survival." (PMID 32231717, 2020). "In contrast to that study, this study found that VISTA was mainly expressed in CD68+ macrophages (mean = 32.58%) in breast cancer and in CD4+ T cells (mean = 4.97%), and lower levels of VISTA were found in CD8+ cytotoxic cells (mean = 4.48%)." (PMID 33250890, 2020). "It remains to be determined if the suppression of antigen presentation in CD4+ T cells and CD8+ T cell activation in the tumor microenvironment of HFD offspring is causally linked to their increased mammary cancer growth and risk of recurrence." (PMID 32580156, 2020).